PTH (parathyroid hormone)
Diseases named in the same sentence as PTH in open-access papers (continued):
Sharing a sentence is not in itself a finding about the gene and the disease.
acute pancreatitis (4 papers, 2015 to 2026). An acute inflammatory process that leads to necrosis of the pancreatic parenchyma. "Laboratory tests showed extremely high calcium levels (4.45 mmol/L), elevated parathyroid hormone (PTH), and markers of acute pancreatitis and kidney dysfunction." (PMID 40177427, 2025).
age (4 papers, 2020 to 2025). A temporal measurement of the time period elapsed since an identifiable point in the life cycle of an organism. "Therapeutic strategies aimed at fine-tuning PTH delivery (e.g., pulsatile analogs) or modulating PTH-induced content may open new avenues for treating age-related musculoskeletal and NMJ degeneration, particularly in conditions like osteosarcopenia or sarcopenic neurodegeneration." (PMID 40806191, 2025). "In summary, PTH may reduce the accumulation of senescent cells in subchondral bone by inhibiting p16ink4a and improve bone marrow microenvironment to active bone remodelling process, indicating PTH administration could be a potential preventative and therapeutic treatment for age‐related TMJ OA." (PMID 32154622, 2020).
Alkalosis (4 papers, 2014 to 2025). Depletion of acid or accumulation base in the body fluids. "Transient perturbations in parathyroid hormone, calcium, and phosphorus may explain why alkalosis preceded Charcot foot 100% of the time." (PMID 24868558, 2014).
Autoimmunity (4 papers, 2003 to 2025). The occurrence of an immune reaction against the organism's own cells or tissues. "Calcitriol was shown to ameliorate autoimmunity and exhibit transcriptional repression of the parathyroid hormone through recruitment of HDAC2." (PMID 29776409, 2018). "Interestingly, the PTH-rP-specific CTL response obtained after vaccination could not engender any autoimmunity sign in vivo observed by the histology of organs from vaccinated mice, excluding the caveat to the cellular response against self tissues after vaccination with this construct." (PMID 12838324, 2003). "The immune response capacity and the absence of any sign of toxicity and/or autoimmunity in vivo suggest the GC90/IRIV vaccine as a valid tool for active specific immunotherapy of human cancers and metastases overexpressing PTH-rP." (PMID 12838324, 2003).
calcium deficiency rickets (4 papers, 2010 to 2022). "In children with dietary calcium-deficiency rickets, high production rates of 1,25(OH)2D probably represent an exaggerated parathyroid hormone (PTH)–mediated stimulation of 1α-hydroxylase owing to inadequate calcium intake." (PMID 20499377, 2010). "Children with calcium deficiency rickets may have normal calcium due to the compensatory effects of parathyroid hormone to maintain the serum calcium however parathyroid hormone was not measured in this study." (PMID 30373538, 2018). "Group A had the characteristic biochemical profile of children with active calcium-deficiency rickets of elevated TALP, PTH and 1,25(OH)2D concentrations, lower plasma calcium and phosphate concentrations and increased urinary phosphate loss." (PMID 32276153, 2020).
cardiac ischemia (4 papers, 2019 to 2025). "In addition, our data suggest that levels of PTH > 300 pg/mL might also represent a high risk of HD-induced myocardial ischemia, suggesting this hormone might increase the risk of myocardial stunning, although whether this is an independent risk factor warrants further investigation." (PMID 30787343, 2019). "PTH evinces its effects through PTH 1 receptor which is expressed in cardiomyocytes, vascular smooth muscle cells, and endothelial cells and which level is increased during myocardial ischemia, cardiac fibrosis, and aging." (PMID 31597282, 2019).
cherubism (4 papers, 2012 to 2024). Cherubism is a rare, self-limiting, fibro-osseous, genetic disease of childhood and adolescence characterized by varying degrees of progressive bilateral enlargement of the mandible and/or maxilla, with clinical repercussions in severe cases. "Other benign lesions included in the differential diagnosis include: Brown tumors, which are usually multiple lesions and result from increased parathyroid hormone levels, as well as cherubism, which is a congenital disorder causing marked expansion of all 4 quadrants of the jaw." (PMID 31319877, 2019). "Both HPT-JT and FIHP can be distinguished from cherubism on the basis of increased levels of PTH, serum calcium, serum phosphorus and alkaline phosphatase." (PMID 38281202, 2024).
cholelithiasis (4 papers, 2018 to 2025). The presence of crystallized deposits forming in the gallbladder or biliary tree, primarily composed of cholesterol, bilirubin, and bile. "In their study, cholelithiasis was detected in 25% of patients with high PTH level compared with 2.6% of patients with normal PTH level." (PMID 29301445, 2018). "Moreover, patients with cholelithiasis presented significantly elevated levels of both calcium (12.03 mg/dL vs. 11.06 mg/dL; p < 0.05) and PTH (357 pg/mL vs. 298.52 pg/mL; p < 0.05)." (PMID 39941666, 2025).
coronary atherosclerosis (4 papers, 2022 to 2025). Atherosclerosis of the coronary vasculature. "Therefore, athletes who train multiple hours per week, often at high intensity, may expose themselves repeatedly to PTH elevations, which could potentially contribute to accelerated coronary atherosclerosis." (PMID 39957063, 2025). "This indicates that our exercise protocol was of sufficient duration and intensity to increase PTH levels but did not reveal differences between the coronary atherosclerosis groups." (PMID 39957063, 2025).
Crohn disease (4 papers, 2019 to 2025). A gastrointestinal disorder characterized by chronic inflammation involving all layers of the intestinal wall, noncaseating granulomas affecting the intestinal wall and regional lymph nodes, and transmural fibrosis. "Anti-TNF-α therapy in Crohn’s disease, a disorder characterized by overproduction of TNF-α resulted in higher levels of PTH." (PMID 33861790, 2021).
dental fluorosis (4 papers, 2021 to 2024). A condition that results from excessive fluoride ingestion during tooth development, resulting in tooth discoloration ranging from white streaks to brown stains and cracks or pits in the tooth enamel. "After adjusting for confounding factors, including urinary fluoride, maternal education level, and per capita annual household income, multivariate Logistic regression analysis showed that BALP, OC, MMP-2, MMP-9, and PTH were independently associated with the risk of dental fluorosis (P<0.05)." (PMID 39876909, 2024). "The urine fluoride levels, BALP, MMP-2, and MMP9 of the children in the fluorosis group were higher than fluoride-free group, and the mother's educational level, per capita annual household income, OC, and PTH were lower than fluoride-free group (P<0.05)." (PMID 39876909, 2024). "High BALP, MMP-2, MMP-9, low OC, and PTH are independent factors affecting the occurrence of dental fluorosis and are related to the extent of dental fluorosis." (PMID 39876909, 2024). "In summary, high BALP, MMP-2, MMP-9, and low OC, PTH are independent factors affecting the occurrence of dental fluorosis and are related to the urinary fluoride level and the extent of dental fluorosis." (PMID 39876909, 2024). "Considering the potential role of VDR and PTH in amelogenesis, as well as the limited evidence about the association between DDE and these genes, this cross-sectional study aimed to investigate the association between DDE (excluding dental fluorosis) and SNPs in the genes encoding VDR and PTH." (PMID 38922252, 2024). "The aim of this study was to investigate the association between dental fluorosis occurrence in children and bone metabolism-related indicators, including bone-specific alkaline phosphatase (BALP), osteocalcin (OC), matrix metalloproteinase (MMP-2, MMP-9, MMP-20), and parathyroid hormone (PTH)." (PMID 39876909, 2024). "As the urinary fluoride level and the extent of dental fluorosis increased, there was a gradual elevation in serum BALP, MMP-2, and MMP-9 levels in children, while OC and PTH levels gradually decreased (P<0.05)." (PMID 39876909, 2024).
Eiken syndrome (4 papers, 2023 to 2025). Eiken syndrome is a rare familial skeletal dysplasia characterized by multiple epiphyseal dysplasia, with extremely retarded ossification. "Homozygous mutation of E35, which is located at the N-terminal end of α1 helix and which makes contacts to the variant residues 16 and 19 in PTH/PTHrP, is found in the rare Eiken syndrome characterized by delayed bone mineralization and epiphyseal dysplasia." (PMID 38331475, 2024). "Patients with delayed ossification (Eiken syndrome) can exhibit features of both gain-of-function effects of the mutant PTH1R toward PTHrP in developing bone but also loss-of-function effects toward PTH in the kidney (PTH-resistance) or toward PTHrP in developing teeth (PFTE)." (PMID 40904804, 2025). "Our overall findings thus suggest that the three different Eiken syndrome mutations can have different effects on the receptor, including both gain and loss of function effects, depending on the cell type expressing the receptor and the intended endogenous ligand, PTH or PTHrP." (PMID 37268817, 2023). "PTH1R mutations have been reported in conditions such as Blomstrand chondrodysplasia and Eiken syndrome, which may present with variable skeletal findings and end-organ PTH resistance." (PMID 41322012, 2025). "The other clinical manifestations of Eiken syndrome, however, such as the mild PTH resistance and PFTE, are more likely explained by a loss-of-function effect on PTH1R signaling responses in kidney and teeth, as mediated by PTH and PTHrP, respectively." (PMID 40904804, 2025). "For some of the Eiken syndrome patients, however, additional clinical phenotypes were reported that seem more consistent with a loss-of-function (LOF) effect of the mutation, particularly on PTH-mediated calcium homeostasis." (PMID 37268817, 2023).
Hearing impairment (4 papers, 2015 to 2023). A decreased magnitude of the sensory perception of sound. "The serum levels of FGF23, phosphorus, and parathyroid hormone (PTH) in ESRD patients with hearing impairment significantly increased compared with those with normal hearing and healthy controls." (PMID 34721981, 2021).
hepatocellular carcinoma (4 papers, 2013 to 2025). A malignant tumor that arises from hepatocytes. "There were four enriched KEGG terms: endocrine resistance (p = 6.03 × 10−3), parathyroid hormone synthesis, secretion, and action (p = 1.38 × 10−3), chemical carcinogenesis- receptor activation (p = 2.47 × 10−2), and hepatocellular carcinoma (p = 2.88 × 10−2)." (PMID 40501859, 2025). "It was reported that 8 to 68% of 44 patients with hepatocellular carcinoma had increased levels of α- and β-human chorionic gonadotropin (hCG) subunits, calcitonin, parathyroid hormone (PTH), prolactin (PRL), adrenocorticotropic hormone (ACTH) and growth hormone (GH)." (PMID 24137355, 2013).
Hypercholesterolemia (4 papers, 2020 to 2022). An increased concentration of cholesterol in the blood. "Both OC and 25(OH)D, rather than PTH, were associated with abnormalities of high cholesterol levels, such as hypercholesterolemia and high LDL-C levels." (PMID 33833796, 2021).
hypophosphatasia (4 papers, 2016 to 2024). Hypophosphatasia (HPP) is a rare heritable metabolic disorder characterized by defective mineralization of bone and/or teeth in the presence of reduced activity of unfractionated serum alkaline phosphatase (ALP). "Conditions associated with low serum PTH include idiopathic infantile hypercalcaemia, Williams-Beuren syndrome and inborn errors of metabolism, including hypophosphatasia." (PMID 33990852, 2022).
Impaired glucose tolerance (4 papers, 2014 to 2023). An abnormal resistance to glucose, i.e., a reduction in the ability to maintain glucose levels in the blood stream within normal limits following oral or intravenous administration of glucose. "Studies have shown that increased PTH was associated with impaired glucose tolerance and decreased insulin sensitivity." (PMID 25254046, 2014). "Further on, a positive relationship was found between preptin and PTH and osteocalcin, respectively, in the whole group and impaired glucose tolerance group." (PMID 37755271, 2023). "Possible mechanisms that might explain the reported association between inadequate vitamin D status and impaired glucose tolerance are related with the widespread presence of vitamin D receptors in tissues or, alternatively, to indirect effects that are mediated by changes in calcium and PTH." (PMID 35057492, 2022). "In a cohort of 73 hemodialysis (HD) patients with a mean HD vintage of 69.7 months, a median parathormone (PTH) of 227 pg/mL and median ALP of 92 U/L, preptin levels were similar in subjects with impaired glucose tolerance versus individuals with normal carbohydrate metabolism." (PMID 37755271, 2023).
metabolism (4 papers, 2015 to 2025). "Conversely, only in men, serum calcium level was positively associated with impaired glucose metabolism (indexed by fasting blood glucose) in a cross-sectional study with 480 T2DM patients; and this association was independent of PTH or bone metabolism." (PMID 25924883, 2015).
mineral metabolism disorders (4 papers, 2011 to 2024). "An increase in serum PTH level has been reported to stimulate the release of Ca and P from bones, resulting in mineral metabolic disorders and vascular calcification in patients with CKD." (PMID 36309659, 2022). "Patients with ESRD on peritoneal dialysis manifest a high prevalence of mineral metabolism disorders, including elevated concentrations of serum phosphorus, parathyroid hormone (PTH), and decreased calcium." (PMID 27661984, 2016).
myasthenia gravis (4 papers, 2017 to 2025). Myasthenia gravis (MG) is a rare, clinically heterogeneous, autoimmune disorder of the neuromuscular junction characterized by fatigable weakness of voluntary muscles. "The blood count, blood biochemistry, thyroid function, parathyroid hormone, blood acylcarnitines and urine organic acid profiles, paraneoplastic antibody spectrum, and antibodies of myasthenia gravis were all negative." (PMID 34978387, 2022). "The blood count, blood biochemistry, thyroid function, parathyroid hormone, blood acylcarnitines and urine organic acid profiles, and antibodies of myasthenia gravis were all negative." (PMID 34978387, 2022).
neuroendocrine tumor (4 papers, 2018 to 2024). "Finally, ectopic production of PTH by a rapidly progressive neuroendocrine tumor was proven." (PMID 39703837, 2024). "Liver biopsy revealed a neuroendocrine tumor with histological staining showing a negative result for synaptophysin and chromogranin, but a positive result for PTH." (PMID 39703837, 2024).
orthostatic hypotension (4 papers, 2020 to 2025). Sudden fall of the blood pressure of at least 20/10 mm Hg when a person stands up. "Vasodilation-mediated TEAEs, such as orthostatic hypotension, are a potential complication of treatment with a PTH agonist." (PMID 39574220, 2025).
pheochromocytoma (4 papers, 2020 to 2025). "In our case, the elevation of intact PTH and its spontaneous normalization after surgical treatment of pheochromocytomas confirms its ectopic secretion." (PMID 32832168, 2020).
prediabetes (4 papers, 2020 to 2024). "We have also reported that vitamin D deficiency, in combination with increased PTH, is associated with higher fasting glucose profiles in elderly individuals with prediabetes and patients with co-existing NPHPT and prediabetes, compared to individuals with prediabetes per se." (PMID 33207657, 2020).
psychosis (4 papers, 2023 to 2026). "Our patient's novel clinical presentation revealed elevated PTH and normal calcium levels as the cause of her psychosis." (PMID 37033554, 2023). "The PTH levels in patients with schizophrenia, bipolar disorder type 1, and methamphetamine-induced psychotic disorder were lower than in the control group (p < 0.001)." (PMID 37803327, 2023). "Finally, by evaluating serum levels of calcium, phosphorus, and PTH in addition to vitamin D and CRP, we aimed to find a new cause for starting psychotic disorders and discovering a screening tool for differentiating chronic with new-onset psychotic disorders." (PMID 37803327, 2023).
squamous carcinoma (4 papers, 2017 to 2025). "To address whether the secreted PTH increases [Ca2+]i in keratinocytes, we first monitored [Ca2+]i following the addition of hPTH1-34 agonist (1 nM and 1 μM) in the culture medium of C5N (derived from normal mouse keratinocytes) and B9 (derived from mouse squamous cell carcinoma) cells." (PMID 28894263, 2017).
steatosis (4 papers, 2022 to 2024). Increased lipid within the cytoplasm of cells. "Ordinal regression analysis for PTH with postoperation steatosis (ultrasonography) was studied after adjusting by baseline WC, age, ALP, gender, AST, GGT, ALT, and HOMA-IR on subject groups." (PMID 35265372, 2022). "We next investigated whether PTH affects acute fasting-induced steatosis, which is attributed to excess serum free fatty acid released by adipocytes." (PMID 36060945, 2022). "Patients with moderate/severe steatosis had high levels of alpha-2 (%) and alpha-2, triglycerides, ferritin, cholinesterase, GPT, PTH Intact, and WBC, p < 0.05." (PMID 37242264, 2023).
viral infections (4 papers, 2023 to 2025). "Many etiologies to otosclerosis have been proposed, including differences in TGFβ, parathyroid hormone or angiotensin II signalling, alterations in collagen type I, inflammation, viral infection, and autoimmunity." (PMID 36653343, 2023). "Patients on peritoneal dialysis are known to have a significantly increased risk for AP due to contributing factors such as alterations in serum calcium and parathyroid hormone levels, bacterial and viral infections, and toxic substances in the PD dialysate." (PMID 37208706, 2023).
acute myeloid leukemia (3 papers, 2021 to 2022). Acute myeloid leukemia (AML) is a group of neoplasms arising from precursor cells committed to the myeloid cell-line differentiation. "Our analysis found that TFs with maximum interactions are involved in cancer, hepatitis B and C, acute myeloid leukemia, and human T-cell leukemia virus 1 infection, mitophagy, cytosolic DNA-sensing pathway, and parathyroid hormone activity." (PMID 33795737, 2021). "KEGG pathway enrichment analyses revealed that the DEGs participated in acute myeloid leukemia (p = 0.04), TGF‐β signaling pathway (p = 0.04), endocrine resistance (p = 0.04), and parathyroid hormone synthesis, secretion, and action (p = 0.04)." (PMID 34741430, 2021).
Adrenal insufficiency (3 papers, 2010 to 2025). Insufficient production of steroid hormones (primarily cortisol) by the adrenal glands. "Another interesting aspect is that in our study vitamin D concentration was higher in the adrenal insufficiency group, while controls had higher PTH concentrations." (PMID 36407318, 2022).
Aminoaciduria (3 papers, 2010 to 2025). An increased concentration of an amino acid in the urine. "Later on, it was shown that PTH levels were actually increased in stage 1 of VDDR at a time when the phosphaturia or aminoaciduria were still absent." (PMID 21274319, 2010).
Arthritis (3 papers, 2014 to 2022). Inflammation of a joint. "Our study is the first to investigate and demonstrate the combined effect of PTH and a bisphosphonate in arthritis." (PMID 24637846, 2014). "The aim of the study was in experimental arthritis to investigate the juxtaarticular and systemic effects of simultaneous osteoclast inhibition with zoledronate (ZLN) and osteoblast stimulation with parathyroid hormone (PTH)." (PMID 24637846, 2014). "Longitudinal samples from 14 progressors demonstrated a consistent increase in 25(OH)D levels at the time they exhibited clinically detectable joint inflammation, without any significant change in VDBP or PTH levels." (PMID 31557191, 2019). "In clinical or experimental arthritis, no study has yet investigated the combined effect of ZLN and PTH." (PMID 24637846, 2014).